OCLN (occludin)
Diseases named in the same sentence as OCLN in open-access papers (continued):
Sharing a sentence is not in itself a finding about the gene and the disease.
cerebral infarction (13 papers, 2015 to 2025). An ischemic condition of the brain, producing a persistent focal neurological deficit in the area of distribution of the cerebral arteries. "According to the results of other authors, the blood concentration of occludin and claudin correlated with the risk of hemorrhagic conversion of cerebral infarct." (PMID 33182224, 2020). "Furthermore, the results suggest that decreased expression of occludin might be associated with the exacerbation of cerebral infarction." (PMID 36806348, 2023). "Few studies have examined the effects of directly regulating occludin expression on cerebral infarction." (PMID 36806348, 2023). "Postoperative serum occludin levels were also correlated with the volume of cerebral infarction, 24‐h NIHSS score, and 90‐day functional outcome after successful EVT." (PMID 35338575, 2022). "The results demonstrated that there was a significant correlation between serum occludin levels and cerebral infarction volume after thrombectomy (r = 0.698, p < 0.001)." (PMID 35338575, 2022). "In the moderate and severe cerebral infarction (CI) groups, serum occludin levels were significantly higher than those in the mild CI group (P<0.001)." (PMID 33269096, 2020). "We also analyzed the serum occludin level in the cerebral infarction patient (n=171), which included 19 with intracranial HT and 147 without intracranial HT." (PMID 33269096, 2020). "There are studies that have shown that Ang-1 protects blood-brain barrier permeability and cerebral infarct size by upregulating ZO-1, occludin, and VE-cadherin." (PMID 30729120, 2019). "A recent study suggested that Ang-1 decreases BBB permeability and brain infarct volumes in middle cerebral artery occlusion and reperfusion in rats and that these effects are related to the ability of Ang-1 to upregulate ZO-1, occludin, and VE-cadherin." (PMID 28355299, 2017). "Our occludin-deficient mouse study shows that a decrease in occludin exacerbates neurological deterioration, accompanied by an expansion of infarct volume and BBB dysfunction after cerebral infarction." (PMID 36806348, 2023). "In addition, other tight junction proteins such as ZO-1 and occludin are also important targets in clinical studies of cerebral infarction." (PMID 35892657, 2022). "In addition, postoperative serum occludin levels were correlated with the volume of cerebral infarction, 24‐h NIHSS score, and 90‐day functional outcome for patients who underwent EVT with successful reperfusion." (PMID 35338575, 2022). "At the same time, Claudin-5 and occludin were degraded by MMP2, the BBB was destroyed and the size of cerebral infarction increased." (PMID 35959401, 2022). "In this study, the hairy root extract of AG inhibits the brain infarction, edema, and BBB leakage in MCAO-induced ischemic rats through the inhibition of glial activation, and the increase of Ang-1, Tie-2, VEGF and tight junction proteins, ZO-1 and Occludin and the activation of PI3K/Akt." (PMID 25888524, 2015).
Hypertension (13 papers, 2011 to 2025). The presence of chronic increased pressure in the systemic arterial system. "In our study, hypertension weakened tight junction proteins such as ZO-1 and Occludin, which led to increased intestinal permeability and bacterial translocation." (PMID 39767618, 2024). "Moreover, in models of cardiac arrest and lateral percussion-induced TBI, NaHS stabilizes the BBB by inhibiting MMP-9 and occludin, prevents vascular dysfunction, hypertension, and sympathetic hyperactivity, and restores CBS, CSE, and eNOS expression." (PMID 41465271, 2025). "Owing to hypertension, circulating pro-inflammatory cytokines and angiotensin II from the periphery act on the angiotensin II type 1 receptor on the BBB endothelium, thus causing the disruption to tight junction proteins and occludin." (PMID 38696405, 2024). "Interestingly atorvastatin has been shown to increase patency of the BBB in a hypertension model, by increasing expression of two tight junction proteins, zonula occludens-1 and occludin." (PMID 21453520, 2011). "So far, experimental animal studies have shown a negative effect of arterial hypertension on the distribution and function of ZO-1 and occludin, which we have also found in relation to ZO-1 in our patients." (PMID 33182224, 2020).
enteritis (12 papers, 2021 to 2025). Inflammation of the small intestine. "In this study, V9 increased the expression of Occludin and ZO-1 in the intestinal mucosa of mice with enteritis." (PMID 39926427, 2025). "In our study, Claudin3 and Claudin8 decreased and Occludin increased after C. perfringens treatment, suggesting that C. perfringens-induced enteritis can partially disrupt intestinal tight junction proteins and increase intestinal permeability." (PMID 40869997, 2025). "Our experiments revealed that LLC tumor-bearing mice suffered from severe enteritis, and the protein levels of Occludin and ZO-1 in colon tissue were significantly reduced, leading to impaired intestinal barrier function." (PMID 39594117, 2024). "The findings of this study indicated that the expression of TJs (ZO-1 and occludin) was significantly reduced in enteritis mice, leading to a disruption in intestinal barrier function." (PMID 37375702, 2023). "A large number of in vitro experiments proved that TGEV reduces the protein levels of Claudin-1, Occludin and ZO-1 in IPEC-J2 cells, which is closely related to its cause of viral enteritis, diarrhea and morbidity in piglets." (PMID 36052062, 2022). "In terrestrial animals, studies on broilers showed that MOS could reduce the concentration of serum DAO and endotoxin, and maintain intestinal Occludin and Claudin-3 expression under enteritis model conditions." (PMID 35624670, 2022). "In a study of LPS-induced gosling enteritis, it was found that RAMP increased the levels of intestinal tight junction proteins occludin and ZO-1 and improved intestinal flora disturbance, thereby relieving gosling enteritis." (PMID 36034948, 2022).
Chronic colitis (11 papers, 2015 to 2025). A chronic inflammatory disease of the large intestine (colon, cecum and rectum). "We found that after the treatment of monotropein, the tight junction proteins occludin and ZO-1 in the intestinal tract of chronic colitis mice were significantly upregulated." (PMID 40041493, 2025). "LWE also restored goblet cell numbers and reduced fibrosis in DSS-induced chronic colitis mice, increasing gene and protein expressions of ZO-1 and occludin." (PMID 39061864, 2024). "Occludin protein expression was significantly decreased in the colonic tissue of chronic colitis model mice, and CsA mitigated this reduction." (PMID 39512421, 2024). "Our research findings demonstrate a positive correlation between the levels of β-hydroxybutyrate in rats with chronic colitis and the tight junction proteins OCLN and CLDN5, with a strong tendency towards a positive correlation with ZO-1." (PMID 37513865, 2023). "Quantitative real-time PCR revealed that two key tight-junction proteins (occludin and ZO-1) were decreased in the colons of chronic colitis mice and were significantly decreased in mice treated with four cycles of DSS + water." (PMID 26013555, 2015). "Monotropein treatment in chronic colitis mice could increase the expression of occludin and ZO-1 in a dose-dependent manner." (PMID 40041493, 2025). "In summary, decreases in E-cadherin, ZO-1, and occludin protein levels were detected in chronic colitis and acute colitis model mice, and compared with uncoated CsA NPs, LM-CsA NPs promoted intestinal barrier repair and increased intestinal barrier protein expression." (PMID 39512421, 2024). "However, administration of BMS-477118 at both 5 mg/kg and 10 mg/kg doses led to a significant upregulation of ZO-1 and OCLN expression compared to the untreated chronic colitis group." (PMID 39359253, 2024). "Therefore, the protective effects of (R)-sal in PAS, ZO-1, and occludin were further investigated in mice with chronic colitis." (PMID 35178163, 2022). "Similar to previous researches, the expressions of ZO-1, occludin, and glycogen proteins were noticeably suppressed compared with the control group, which reflected that the intestinal barrier was damaged in mice with chronic colitis." (PMID 35178163, 2022). "In chronic colitis induced by DSS, occludin expression is significantly reduced, indicating a compromised intestinal barrier and increased permeability." (PMID 40502390, 2025). "In another DSS-induced chronic colitis model, both LF ST36 EA and HF ST36 EA increased the level of colonic proteins ZO-1, Occludin, E-cadherin, and MUC2, and this finding showed that EA can protect the mucus layer from bacteria penetration." (PMID 35095910, 2021).
diabetic retinopathy (11 papers, 2015 to 2025). "Suppression of Cln5 and occludin mediated by VEGF upregulation has also been associated with barrier breakdown in mouse models of diabetic retinopathy and oxygen-induced retinopathy (OIR) modeling retinopathy of prematurity." (PMID 37887287, 2023). "Loss of occludin and disrupted tight junctions are a feature of diabetic retinopathy, and this feature has also been reported in placental vessels in pregnancies complicated with GDM." (PMID 33001231, 2021). "VME treatment reduced specific indicators of diabetic retinopathy, such as the degradation of OCLN (occludin), ZO-1 (zonula occludens-1), CLDN5 (claudin-5), and VEGF (retinal vascular endothelial growth factor) expression in diabetic rats." (PMID 37836403, 2023). "Reduced retinal occludin expression resulting in increased iBRB permeability has been reported both in rodent model of diabetic retinopathy and in vitro studies, while JAM-C maintains TJ integrity." (PMID 37887287, 2023). "MMP-9 is known to degrade occludin and claudin-5 in focal cerebral ischemia, and it has been reported that it affects the expression of occludin, claudin-5, and ZO-1 and ZO-2 levels in early diabetic retinopathy." (PMID 32178308, 2020). "Increased presence of miR-181a-5p in the circulation could lead to downregulation of occludin in different organs and may be behind diabetic retinopathy or nephropathy." (PMID 33001231, 2021). "At these sites, although occludin tight junctions may limit the penetration of intravitreally injected proteins, studies have also shown that in a disease state such as diabetic retinopathy or hypoxia, these tight junctions may be damaged allowing protein penetration." (PMID 31827177, 2019). "In research on diabetic retinopathy, VEGF and MMP-9 are shown to regulate ZO-1 and occludin in retinal vascular endothelial cells; however, in this study, we discovered a novel signaling pathway that can modulate ZO-1 and occludin." (PMID 37430272, 2023). "Activation of SIRT1 by Resveratrol maintains the epithelial barrier by increasing the expression of TJ proteins ZO1, Occludin and Claudin1, while it negatively regulates MMP9 in diabetic retinopathy, and reduction of SIRT1 levels through oxidative stress confers an increase in MMP9." (PMID 39086962, 2022).
irritable bowel syndrome (11 papers, 2015 to 2025). Irritable bowel syndrome (IBS) is a chronic functional condition of the lower gastrointestinal (GI) tract characterized by abdominal pain or discomfort and disordered bowel habit (diarrhea, constipation, or fluctuation between the two). "Irritable bowel syndrome, especially IBS following infectious enteritis, is associated with decreased occludin at tight junctions and increased colonic mucosal permeability." (PMID 36825261, 2022). "For example, TJ proteins ZO-1 and occludin were decreased in irritable bowel syndrome." (PMID 30210262, 2018). "In a model of stress-induced irritable bowel syndrome (IBS), the same group found that fermented soy germ extract also prevented the decreases in occludin expression resulting from prolonged stress when compared to non-supplemented controls." (PMID 33916612, 2021). "Moreover, a recent animal study demonstrated that rifaximin promoted the expression of occludin, the major TJP, in an irritable bowel syndrome mouse model." (PMID 32235367, 2020). "Similarly, the expression of clauidn-1, claudin-7, JAM-A, occludin, and ZO-1 in the ileal, cecal, and rectal mucosa did not change between control and diarrhea-predominant irritable bowel syndrome samples." (PMID 28366996, 2017).
viral infection (11 papers, 2020 to 2025). "Because disruption of the blood-tissue barrier during viral infection is mostly associated with the degradation or redistribution of TJPs, we assessed the staining of key TJPs, such as ZO-1, claudin-1, and occludin, by immunofluorescence analysis." (PMID 32302362, 2020). "The studies usually show that viral infection leads to a decrease in the expression of ZO-1, occludin, and claudin proteins, followed by the apoptosis of infected cells, as demonstrated for HSV-1 and Zika virus." (PMID 41439958, 2025). "Beyond its structural role, Occludin acts as a dual-function regulator during viral infections: it serves as both a molecular gateway for viral entry and a mediator of barrier disruption, thereby amplifying viral spread." (PMID 40142587, 2025). "The involvement of OCLN in viral infection and replication was further examined by comparing virus responses of cells in which OCLN expression had been reduced by siRNA silencing and controls in which ACE2 knockdown had been performed." (PMID 37068248, 2023). "OCLN knockdown significantly inhibited virus infection and S protein–mediated syncytium formation with each of the virus strains, which is consistent with our previous findings." (PMID 37068248, 2023). "During viral infection, the expression of ZO-1 and OCLN is significantly downregulated, thereby breaking the integrity of the BBB." (PMID 36297257, 2022). "Other viruses that cause diarrhea, such as rotavirus, can infect intestinal epithelial cells and the distribution of tight junction proteins Claudin-1 and Occludin, thereby promoting viral infections." (PMID 33804466, 2021). "We wondered whether TJ proteins (Occludin, Claudin and ZO-1) play a role in viral infection and whether it interact with the VP2 protein." (PMID 40142587, 2025). "The noticeable depletion of occludin is induced by bacterial and viral infection." (PMID 33561923, 2021). "In addition, both viral infection and perturbed gut microbiota have the potential to disturb the normal function of the gut barrier and lead to impaired intestinal permeability and the degradation of tight junction proteins, such as occludin, junctional adhesion molecule-A, and claudin-1." (PMID 38675974, 2024). "Knockdown of OCLN in SARS-CoV-2permissive Vero-E6 and A549-hACE2 cells does not impact ACE2 expression but significantly reduces virus infection, especially during the internalization stage and subsequent viral replication." (PMID 37068248, 2023). "In the colon of rhesus monkeys infected by chronic SIV, mRNA expression of OCLN and CLDN3 is downregulated, and then favoring viral infection." (PMID 36297257, 2022). "The changes in gene expression of ZO-1, Occludin, and Claudin-1 in this study suggest the destruction of ileal TJs after XMX infection, which can be observed in other reports about viral infection." (PMID 35891451, 2022). "IAV virus subtype H3N2 promotes viral infection by downregulating the expression of ZO-1, CLDN1 and OCLN when infecting ferret nasal epithelial cells." (PMID 36297257, 2022). "Therefore, our results demonstrating occludin modulation of OAS gene expression may further elucidate the pathology of autoimmune diseases and several viral infections." (PMID 37209263, 2023).
edema (10 papers, 2013 to 2025). An abnormal accumulation of fluid beneath the skin, or in one or more cavities of the body. "Early HBO therapy mitigates blood–brain barrier disruption and suppresses the progression of brain edema post-ICH by preventing occludin degradation and matrix metalloproteinase-9 activation in the perihematomal tissue." (PMID 26073666, 2015). "We further evaluated its effectiveness against pulmonary edema by checking the mRNA expression level of HO-1 enzyme, occludin, and TJ proteins (ZO-1) in the lung tissue of the normal and asthmatic mice before and after the treatment with J. regia L. by using real-time PCR." (PMID 40421046, 2025). "Reduces peritumoral inflammation and cerebral edema DEX ameliorated cerebral edema by reducing the permeability of blood‐brain barrier, through regulating the expression level of occludin, claudin, and vascular endothelial (VE)‐cadherin thereby improving symptoms." (PMID 40014265, 2025). "However, fingolimod significantly aggravated brain edema and reduced the expression levels of tight junction proteins ZO-1 and Occludin." (PMID 32848587, 2020). "In line with the mechanisms of UVB skin edema and RvD1 effects, RvD1 attenuates pulmonary edema in a model of lipopolysaccharide (LPS)-induced acute lung injury by reducing occludin and zona occludin-1 tight junction proteins deterioration and vascular injury-induced neointimal hyperplasia." (PMID 30429790, 2018). "In agreement with our findings, recent evidence supports that the stabilization of ZO-1 and occludin expression could relieve pulmonary edema, as a result of enhanced pulmonary barrier function in a mouse model of ALI." (PMID 29874809, 2018). "Our study suggests that fasudil attenuated LPS-induced pulmonary edema via upregulating the expression of AQP5 and TJ protein occludin." (PMID 28963443, 2019). "Our study showed that early relief of severe bilateral carotid stenosis could lead to brain edema and elevation of BBB permeability, which was associated closely with increased activity and expression in MMP-9 and decreased quantity in tight junction proteins claudin-5 and occludin." (PMID 23469092, 2013).
mastitis (10 papers, 2019 to 2026). Inflammation of breast tissue during lactation or postpartum due to an obstructed duct or infection. "Expression of intestinal tight junction proteins (e.g., Claudin-1, Occludin) is significantly downregulated (by ~40%), causing endotoxin translocation (serum LPS increases ~3-fold) and disruption of the blood-milk barrier, increasing mastitis risk by 2-3 times." (PMID 41766889, 2026). "We further investigated the effect of SA on the blood-milk barrier by assessing the expression of the tight junction (TJ) protein ZO-1, Occludin, and Claudin-3, which are disrupted during mastitis." (PMID 37069691, 2023). "The TJ, made up of two major transmembrane spanning structural proteins called Occludin and Claudin 33, 34, play an important role in the immune response during mastitis 35-37." (PMID 31929753, 2020). "Tissue immunofluorescence analysis showed that when compared with the healthy mammary gland, the mammary glands with subclinical mastitis exhibited notably lowered ZO-1, occludin and claudin-1 expressions, as well as clearly elevated LC3 plus beclin-1 expressions at the protein level." (PMID 39765775, 2024). "It has been found, through research, that the occurrence of mastitis will destroy the integrity of tight junctions (TJs), including a decrease in the expression of TJ proteins (claudin-1, occludin, ZO-1, etc.), thereby increasing their permeability and damaging the health of the mammary gland." (PMID 39765775, 2024). "Moreover, Western blotting assay also manifested remarkably decreased ZO-1, claudin-1 and occludin expressions in subclinical mastitis by contrast with those in the healthy ones, while the opposite trends in beclin-1 and LC3 expressions were obtained." (PMID 39765775, 2024).